MRPL12 (mitochondrial ribosomal protein L12)
Description:
As a component of the mitochondrial large ribosomal subunit, plays a role in mitochondrial translation. When present in mitochondria as a free protein not associated with the ribosome, associates with mitochondrial RNA polymerase POLRMT to activate transcription. Required for POLRMT stability.
Synonyms: L12mt; MRPL7; RPML12; MRPL7/L12; bL12m; 5c5-2; MRP-L31/34
Tractability: Small molecule: a structure with a bound ligand is known. PROTAC: UniProt records ubiquitination sites on it; ubiquitination databases record sites on it; its protein half-life has been measured.
Target class: Other cytosolic protein
Gene: Protein-coding gene on chromosome 17 (81,703,367 to 81,707,517, forward strand). Ensembl gene ENSG00000262814.
Subcellular location: Mitochondrion matrix
Subcellular location (Human Protein Atlas): Mitochondria
Pathways (Reactome):
Metabolism of proteins: Mitochondrial protein degradation; Mitochondrial ribosome-associated quality control; Mitochondrial translation elongation; Mitochondrial translation initiation; Mitochondrial translation termination
Gene Ontology:
Molecular function: protein binding; RNA binding; structural constituent of ribosome
Biological process: mitochondrial transcription; positive regulation of DNA-templated transcription; mitochondrial translation; translation
Cellular component: mitochondrial large ribosomal subunit; mitochondrial matrix; mitochondrion; mitochondrial inner membrane; ribosome
Genetic constraint (gnomAD): Loss-of-function variants: 13 observed, 19.71 expected, observed/expected ratio (o/e) 0.66, 90% interval 0.43 to 1.05. The upper end of that interval is the gene's LOEUF score, 1.05, which puts it in group 4 of 6, group 1 being the genes least tolerant of losing a copy. Missense variants: 251 observed, 264.38 expected, observed/expected ratio (o/e) 0.95, 90% interval 0.86 to 1.05. Synonymous variants: 126 observed, 114.41 expected, observed/expected ratio (o/e) 1.1, 90% interval 0.95 to 1.28.
Gene-disease validity (ClinGen):
ClinGen rates the evidence that MRPL12 causes each of these diseases.
mitochondrial disease (autosomal recessive): Limited.
Homologues: Orthologues: chimpanzee MRPL12 (99% identical), dog MRPL12 (88% identical), guinea pig MRPL12 (87% identical), mouse Mrpl12 (86% identical), rat Mrpl12 (85% identical), pig MRPL12 (84% identical), tropical clawed frog mrpl12 (59% identical), zebrafish mrpl12 (57% identical), Caenorhabditis elegans mrpl-12 (34% identical), Drosophila melanogaster mRpL12 (34% identical).
Diseases named in the same sentence as MRPL12 in open-access papers:
MRPL12 is named in the same sentence as 25 diseases in open-access papers, as found by Europe PMC text mining. Sharing a sentence is not in itself a finding about the gene and the disease. The quoted sentences say what the papers report.
breast carcinoma (8 papers, 2021 to 2025). "High MRPL12 expression was weakly but significantly associated with a poor prognosis in breast cancer." (PMID 39859078, 2025). "Knockdown of MRPL12 is associated with decreased metastatic capacity, such as proliferation, migration and cell viability, in aggressive lung and breast cancer cell lines." (PMID 39354291, 2024). "This response to loss of MRPL12, in both LUAD and breast cancer, suggest that it plays a key role in promoting metastatic behaviour and tumour growth." (PMID 39354291, 2024). "In breast cancer, a three-gene prognostic model based on MRPL12, MRPL13, and POP1 has significant predictive value for survival." (PMID 35719986, 2022). "Oval all, we identified three RBP-coding genes (MRPL12, MRPL13 and POP1) that functioned as risk factors and independent prognostic factors for breast cancer." (PMID 34322380, 2021). "Here, we had identified that MRPL12 and MRPL13 also could be regarded as potential risk factors for breast cancer." (PMID 34322380, 2021). "Besides, some compounds (such as the Acetaminophen, Urethane and Tunicamycin) were predicted for curing breast cancer via targeting MRPL12, MRPL13 and POP1 simultaneously." (PMID 34322380, 2021). "MRPL12 is upregulated in many types of cancer, including lung cancer, hepatocellular carcinoma (HCC), and breast cancer." (PMID 39859078, 2025). "In addition, the expression pattern of MRPL12, MRPL13 or POP1 were significantly associated with tumor stage, suggesting that these three RBP-coding genes could be regarded as potential biomarkers for breast cancer prognosis." (PMID 34322380, 2021). "All these results suggested that MRPL12, MRPL13 and POP1 should be designed as biomarkers and potential intervening targets for breast cancer." (PMID 34322380, 2021). "Although MRPL12, MRPL13 or POP1 were over-expressed in tumor tissues, there were also some slight differences in expression pattern between each subtype of breast cancer, wherein TNBC cases tolerated the highest expression of these three RBPs." (PMID 34322380, 2021). "Similarly, knocking down MRPL12 and MRPL13 in vitro significantly inhibits breast cancer cell activity and migration." (PMID 40371222, 2025). "All these results confirmed that MRPL12, MRPL13 and POP1 acted as oncogenes in breast cancer cells, therefore, they might be regarded as prognostic indicators in breast cancer, but also could be designed as therapeutic targets of breast cancer." (PMID 34322380, 2021). "Moreover, analogous to MRPL12 and MRPL13, our results also revealed that POP1 functioned as an oncogene in breast cancer." (PMID 34322380, 2021). "In this context, some strategies that targeting the MRPL12, MRPL13 or even the mitoribosome might be practicable in curing breast cancer." (PMID 34322380, 2021). "These authors concluded that MRPL12, MRPL13, and POP1 might act as oncogenes in maintaining cellular viability and stimulating the metastasis of breast cancer cells, involving the possibility of their being designed as biomarkers and/or therapeutic targets for breast cancer." (PMID 37298568, 2023). "Moreover, the downregulation of endogenous MRPL12, MRPL13, or POP1 expression could significantly inhibit the viability and migration of breast cancer cells in vitro." (PMID 35719986, 2022). "Furthermore, experimental validations showed that down-regulating the expression of endogenous MRPL12, MRPL13 or POP1 could dramatically suppress the cellular viability and migration of breast cancer cells in vitro." (PMID 34322380, 2021). "MRPL12, MRPL13 and POP1 might act as oncogenes in maintaining cellular viability and accelerating metastasis of breast cancer cells, implying the possibility of which to be designed as biomarkers and/or therapeutic targets for breast cancer." (PMID 34322380, 2021).
breast carcinoma (continued). "Furthermore, we performed some preliminary experiments and provided concrete evidence that MRPL12, MRPL13 and POP1 might be oncogenes in maintaining cellular viability as well as accelerating metastasis of the breast cancer cells." (PMID 34322380, 2021). "All these results indicated that MRPL12, MRPL13 and POP1 not only could be designed as prognostic factors for predicting survival probability of patients with breast cancer, but also could be used as potential targets for clinical intervention of breast cancer." (PMID 34322380, 2021). "Notably, by reviewing the Comparative Toxicogenomics Database (CTD), we excavated three available compounds (Acetaminophen, Urethane and Tunicamycin), which could inhibit the MRPL12, MRPL13 and POP1 simultaneously, implying their anti-neoplastic effects on breast cancer." (PMID 34322380, 2021). "Furthermore, down-regulating the expression of endogenous MRPL12, MRPL13 or POP1 in breast cancer cells, resulted in dramatically suppression of cellular viability and migration, suggesting that these three RBP-coding genes might act as oncogenes in accelerating the progress of breast cancer." (PMID 34322380, 2021).
lung carcinoma (6 papers, 2021 to 2025). "Our previous studies have demonstrated that MRPL12 is implicated in various metabolic diseases, including diabetic nephropathy, acute kidney injury, liver cancer, and lung cancer, through its regulation of mitochondrial biosynthesis." (PMID 40858596, 2025). "High expression levels of both MRPL12 mRNA and protein are associated with a poor prognosis in lung cancer as well as HCC." (PMID 39859078, 2025). "Analysis of lung cancer mutation data from the cBioportal database indicated infrequent MRPL12 gene mutations in LUAD, with a frequency of less than 2.5%." (PMID 39343960, 2024). "Furthermore, MRPL44 and MRPL12 were both members of mitochondrial ribosomal proteins, whose abnormal expression was found associated with the tumorigenesis and development of lung cancer." (PMID 34760888, 2021). "MRPL12 enhances cell proliferation, migration, and invasion of lung cancer cells by upregulating mitochondrial oxidative phosphorylation, and its expression levels are inversely associated with the infiltration levels of multiple immune cells." (PMID 39859078, 2025). "For instance, MRPL12 is significantly downregulated in pancreatic cancer, but significantly upregulated in breast and lung cancers." (PMID 40371222, 2025). "MRPL12 is mainly associated with mitochondrial energy supply and the gene LRRC59 is reported to be associated with poor prognosis in lung cancer and is involved in the cell proliferation process." (PMID 35844396, 2022).
lung adenocarcinoma (4 papers, 2021 to 2025). A carcinoma that arises from the lung and is characterized by the presence of malignant glandular epithelial cells. "MRPL12 drives the progression of lung adenocarcinoma by affecting mitochondrial function, specifically mitochondrial OXPHOS." (PMID 40841355, 2025). "Finally, by integrating the results of PPI network analysis and one-way COX regression analysis, we identified six RBPs that are both DEGs and associated with lung adenocarcinoma prognosis—IGF2BP3, SNRPE, GAPDH, MRPL12, MRPL15, and INTS8, with IGF2BP3 being the most differentially expressed." (PMID 40801655, 2025). "However, the biological function of MRPL12 in lung adenocarcinoma (LUAD) remains unclear." (PMID 36769082, 2023). "Upregulation of MRPL22 (HR = 1.5, p = 0.0048), MRPL28 (HR = 1.5, p = 0.0098), MRPL21 (HR = 1.7, p = 0.001), MRPL12 (HR = 1.7, p = 0.00059), MRPS12 (HR = 1.6, p = 0.002), and MRPL17 (HR = 1.5, p = 0.0051) were correlated with poor overall survival in lung adenocarcinoma." (PMID 34925439, 2021). "The Cytoscape with cytoHubba tool kits, GEPIA, and c-BioPortal analysis suggested that upregulated hub genes of MRPL22, MRPL28, MRPL21, MRPL12, MRPS12, and MRPL17 are correlated with poor overall survival and may play a key role by cooperating with ALDOA in lung adenocarcinoma." (PMID 34925439, 2021).
hepatocellular carcinoma (3 papers, 2024 to 2025). A malignant tumor that arises from hepatocytes. "In our previous studies, we explored the role of MRPL12 in regulating mitochondrial metabolism across various metabolic diseases, including diabetic kidney disease, acute kidney injury, hepatocellular carcinoma, and lung adenocarcinoma." (PMID 40858596, 2025).
diabetes (2 papers, 2024 to 2025). "The role of mitochondrial ribosomal protein, L7L12 (MRPL12), in patients with diabetic ischemic heart disease has been examined in right atrial appendage tissues from patients with diabetes undergoing coronary bypass graft surgery." (PMID 40564057, 2025). "Significantly, our prior investigations have linked MRPL12-mediated regulation of mitochondrial biosynthesis, OXPHOS, and metabolism to the pathogenesis of diverse metabolic disorders, including ischemic and hypoxic conditions, as well as diabetes." (PMID 39343960, 2024). "Our previous research emphasized the pivotal role of MRPL12 in modulating mitochondrial OXPHOS and metabolism in various metabolic diseases, including diabetes." (PMID 39343960, 2024).
diabetic kidney disease (2 papers, 2024 to 2025). Progressive kidney disorder caused by vascular damage to the glomerular capillaries, in patients with diabetes mellitus. "Prior investigations have established MRPL12’s involvement in various diseases, such as diabetic kidney disease and hepatic cellular cancer, through the regulation of mitochondrial biogenesis." (PMID 39343960, 2024). "Furthermore, our scrutiny has delved into the transcriptional regulatory and post-translational modification mechanisms of MRPL12 in diabetic kidney disease." (PMID 39343960, 2024). "Our previous investigations revealed that CUL3-mediated ubiquitination modification of MRPL12 influences MRPL12’s protein stability, subsequently leading to dysregulated mitochondrial biosynthesis in renal tubular epithelial cells, contributing to the onset and progression of diabetic nephropathy." (PMID 39343960, 2024). "Our previous studies have shown that mitochondrial ribosomal protein L12 (MRPL12) contributes to various metabolic diseases, including diabetic kidney disease and HCC, by regulating mitochondrial biosynthesis." (PMID 40858596, 2025).
liver cancer (2 papers, 2024 to 2025). An epithelial or non-epithelial malignant neoplasm that arises from the liver. "We found that MRPL12 expression was significantly upregulated and positively associated with worse overall survival in HCC patients, and sorafenib‐treated liver cancer patients whose tumors expressed higher expression of MRPL12 were correlated with lower probability of overall survival." (PMID 38874478, 2024).
adenoma (1 paper, 2024). A neoplasm arising from the epithelium. "KP mice displayed advanced adenocarcinomas, while heterozygous MRPL12 knockout mice showed atypical adenomatous hyperplasia, small adenomas, and low-grade adenocarcinomas." (PMID 39343960, 2024).
dilated cardiomyopathy (1 paper, 2015). Cardiomyopathy which is characterized by dilation and contractile dysfunction of the left and right ventricles. "Mrpl12 (Mitochondrial Ribosomal Protein L12) encodes a nuclear-encoded mitochondrial ribosomal protein essential for mitochondrial protein synthesis that has been associated with disturbed mitochondrial function and dilated cardiomyopathy." (PMID 26555816, 2015).
glioblastoma (1 paper, 2021). The most malignant astrocytic tumor (WHO grade IV). "Furthermore, some evidence suggests that several genes expressing MRPs including bS1m (MRPS28), uS2m (MRPS2), uL23m (MRPL23), uS12m (MRPS12), bL12m (MRPL12) and mS34 (MRPS34) may be potential biomarkers for the treatment of glioblastoma with Benzyl isothiocyanate (BITC)." (PMID 34071057, 2021).
ischemia (1 paper, 2021). A hypoperfusion of the BLOOD through an organ or tissue caused by a PATHOLOGIC CONSTRICTION or obstruction of its BLOOD VESSELS, or an absence of BLOOD CIRCULATION. "At the same time, protein contents of MRPL12 were also reduced by ischemia both in vivo and in vitro." (PMID 34434929, 2021).
lung squamous cell carcinoma (1 paper, 2024). "Conversely, higher MRPL12 expression in lung squamous cell carcinoma did not correlate with poor prognosis." (PMID 39343960, 2024).
tumor (13 papers, 2009 to 2025). "Inhibiting oxidative phosphorylation (OXPHOS) effectively alleviated the tumor-promoting effect caused by overexpression of MRPL12, indicating that MRPL12 participates in the progression of HCC by regulating mitochondrial metabolism." (PMID 39487553, 2024). "We hypothesized that the tumor-suppressive function of MRPL12 acetylation in ccRCC may be linked to metabolic reprogramming." (PMID 40858596, 2025). "This research provides new insight into the function of MRPL12, which could act as a prognostic marker linked to immune cell infiltration and tumor development in LUAD." (PMID 36769082, 2023). "In the current study, we observed low levels of MRPL12 K163 acetylation in ccRCC and identified a strong correlation between MRPL12 K163 acetylation levels, tumor stages, and prognosis in ccRCC patients." (PMID 40858596, 2025). "MRPL12 acetylation at K163 significantly inhibited tumor formation in nude mice, resulting in smaller tumors." (PMID 40858596, 2025). "Further supporting this, the same study found that high expression of MRPL12 was associated with worse prognosis, immune infiltration and poor survival in LUAD tumours." (PMID 39354291, 2024). "Mechanistically, we discovered that MRPL12 promotes tumor progression by upregulating mitochondrial oxidative phosphorylation." (PMID 39343960, 2024). "Immunohistochemical (IHC) analysis of Ad-Cre-treated KP mice showed that MRPL12 expression was upregulated in tumor tissue compared to para-cancerous tissue." (PMID 39343960, 2024). "Remarkably, MRPL12 knockdown led to a significant reduction in tumor growth, evident from decreased tumor volume and weight." (PMID 39343960, 2024). "In line with micro-CT, HE staining revealed decreased tumor burden, smaller nodule size, and fewer nodules in both heterozygous and homozygous MRPL12 knockout mice." (PMID 39343960, 2024). "The xenograft tumor from the MRPL12 WT overexpression group exhibited significantly larger size and weight compared to the control group." (PMID 39343960, 2024). "In contrast, MRPL12 knockout extended the median survival time to about 135 days, indicating that the reduced tumor burden resulting from MRPL12 deletion indeed improved survival." (PMID 39343960, 2024). "As trans-microvascular endothelial migration (TEM) is a crucial step in tumor metastasis, we explored MRPL12’s role in the transmigration of LUAD cells through microvascular endothelium." (PMID 39343960, 2024). "Conversely, both heterozygous and homozygous MRPL12 knockout mice exhibited significantly reduced tumor burden." (PMID 39343960, 2024). "Tumor size, T stage, N stage, pathological stage, chemotherapy, and MRPL12 expression were correlated with the OS of LUAD patients according to the univariate analysis." (PMID 36769082, 2023). "Gene expression analyses in the TIMER database revealed that MRPL12 mRNA expression was significantly overexpressed in multiple tumor tissues in comparison to corresponding normal tissues, including LUAD." (PMID 36769082, 2023). "Three datasets (NSCLC_GSE131907, NSCLC_GSE143423, and NSCLC_GSE146100) from the Tumor Immune Single-cell Hub (TISCH) database were utilized to explore MRPL12 expression in the TME of LUAD." (PMID 36769082, 2023). "Further subgroup analyses of gender, cancer stages, and tumor grade clearly revealed that the protein expression of MRPL12 was higher in LUAD tissues than in normal tissues." (PMID 36769082, 2023). "Other MRPs such as MrpL11, MrpL12 and MrpL28 have been reported to be differentially expressed in tumour cells or tissue." (PMID 28056857, 2017). "We found that knockdown of either mitochondrial ribosomal protein L12 or cytochrome oxidase subunit 4 resulted in a similar increase in tumor growth in vivo." (PMID 19753307, 2009). "Moreover, some studies have found that certain compounds (such as acetaminophen, carbamazepine, and tunicamycin) can exert anti-tumor effects by targeting specific MRPs (such as MRPL12 and MRPL13)." (PMID 40371222, 2025).